RN7SL200P (RNA, 7SL, cytoplasmic 200, pseudogene)
Gene: Miscellaneous RNA gene on chromosome 6 (34,685,355 to 34,685,642, reverse strand). Ensembl gene ENSG00000265123.
Homologues: Orthologues: chimpanzee Metazoa_SRP (99% identical), macaque Metazoa_SRP (92% identical). Paralogues in human: RN7SL2 (87% identical), RN7SL1 (86% identical), RN7SL3 (85% identical), RN7SL126P (83% identical), RN7SL300P (82% identical), RN7SL664P (82% identical), RN7SL220P (82% identical), RN7SL451P (82% identical), RN7SL509P (82% identical), RN7SL383P (81% identical), RN7SL408P (81% identical), RN7SL441P (81% identical), and 702 more.